GPC3 (glypican 3)
Diseases named in the same sentence as GPC3 in open-access papers (continued):
Sharing a sentence is not in itself a finding about the gene and the disease.
gastric tumor (5 papers, 2016 to 2025). "We found that silencing of GPC3 induces expression of FoxM1 in gastric tumor cells, and that is abrogated by MEK inhibition." (PMID 27259271, 2016). "To verify the relevance of GPC3-mediated regulation of FoxM1 in gastric tumors, we performed IHC staining for GPC3 and FoxM1 in 42 primary samples (Wuhan cohort)." (PMID 27259271, 2016). "Here, we evaluate the function of GPC3 in gastric tumors, in particular its ability to regulate mechanisms of tumor cell invasion and metastatic spread." (PMID 27259271, 2016). "Our retrospective analysis of an annotated cohort of gastric tumors establishes an important prognostic value for GPC3." (PMID 27259271, 2016). "In this work, we identify GPC3 as a potential metastasis suppressor gene that controls cellular mechanisms of invasion and metastasis in gastric tumors." (PMID 27259271, 2016). "Earlier reports examining the transcriptional profile of GPC3 showed marked gene down-regulation in gastric tumors, suggesting a potential tumor suppressor role for GPC3." (PMID 27259271, 2016). "However, the precise role of GPC3 in gastric tumor development and progression remains unclear due to the paucity of both pre-clinical and clinical correlative studies." (PMID 27259271, 2016). "To evaluate if the loss of GPC3 affects the metastatic behavior of tumor cells, we decreased the expression of GPC3 in BGC823 and MKN28 gastric tumor cell lines with shRNA (sh-GPC3) and conducted matrigel invasion assays." (PMID 27259271, 2016). "The expression of GPC3 was markedly decreased in gastric but not in esophageal cancer, suggesting an active downregulation of GPC3 in gastric tumor cells." (PMID 31100935, 2019). "Therefore, GPC3 does not seem to be involved in the development of gastric tumors, but it likely impacts disease progression by regulating metastatic spread." (PMID 27259271, 2016).
lymph node metastasis (5 papers, 2019 to 2022). "High Arg-1 and GPC-3 levels, tumor grade, lymph node metastasis, vascular invasion, and TNM stage were risk factors associated with ICC progression." (PMID 34715880, 2021).
choriocarcinoma (4 papers, 2010 to 2023). An aggressive malignant tumor arising from trophoblastic cells. "Because glypican-3 can be also expressed in chorionic carcinoma, this tumour has to be excluded by morphological criteria and expression of β-HCG." (PMID 25889715, 2015). "Within ovarian mixed germ cell tumors, choriocarcinoma was found to be immunoreactive for GPC3, showing strong membranous reactivity with an additional case of endometrial choriocarcinoma in the same study demonstrating similar immunoreactivity." (PMID 20868507, 2010). "No prior studies have been done to investigate the expression of GPC3 in gestational choriocarcinoma, PSTT, or ETT." (PMID 20868507, 2010). "On examination, the pattern of GPC3 in PSTT appears similar but weaker than that seen in gonadal and extra-gonadal choriocarcinoma, with stronger expression mostly limited to larger/multinucleate cells and weaker expression in smaller, mononucleate cells." (PMID 20868507, 2010).
chronic hepatitis (4 papers, 2014 to 2023). An active inflammatory process affecting the liver for more than six months. "While GPC3 was hardly detectable in normal liver and chronic hepatitis, more than 70% of HCC cases showed positive immunoreactivity." (PMID 31510063, 2019). "Some studies showed the serum GPC3 levels tended to be higher in the order of HCC, liver cirrhosis, and chronic hepatitis patients, but its diagnostic utility is still a matter of debate." (PMID 31510063, 2019).
clear cell renal carcinoma (4 papers, 2014 to 2024). A malignant epithelial neoplasm of the kidney characterized by the presence of lipid-containing clear cells within a vascular network. "The data obtained in the present study suggest that GPC3 inhibits cell proliferation in clear cell renal cell carcinoma." (PMID 25168166, 2014). "The GPC3 gene was downregulated in all clear cell renal cell carcinoma samples, with the exception of one." (PMID 25168166, 2014). "The same observation was made in the case of clear cell renal cell carcinoma samples, in which GPC3 gene expression was lower in metastatic samples when compared with non-metastatic samples." (PMID 25168166, 2014). "We observed that GPC3 is downregulated in clear cell renal cell carcinoma samples and cell lines compared with normal renal samples." (PMID 25168166, 2014). "The purpose of this study was to analyze the mechanism of action of the GPC3 gene in clear cell renal cell carcinoma." (PMID 25168166, 2014). "In the present study, GPC3 expression was downregulated in primary clear cell renal cell carcinoma samples and cell lines." (PMID 25168166, 2014). "Five clear cell renal cell carcinoma cell lines and carcinoma samples were used to analyze GPC3 mRNA expression (qRT-PCR)." (PMID 25168166, 2014). "GPC3 gene expression is downregulated in primary clear cell renal cell carcinoma, and GPC3 protein overexpression in clear cell renal cell carcinoma cell lines arrests cells during the G1 phase of the cell cycle, consequently reducing the proliferation rate." (PMID 25168166, 2014). "One of these genes is GPC3, which is decreased in clear cell renal cell carcinoma." (PMID 25168166, 2014).
colon cancer (4 papers, 2018 to 2022). "DWSSWVYRDPQT peptide identified in this study reportedly targets colon cancer cells in vitro with in silico analysis suggesting the peptide targets glypican-3 (a heparin sulphate proteoglycan (HSPG))." (PMID 31902944, 2020). "By immunohistochemistry, the cell line was proven to express the biomarkers of colon cancer CK20 and CDX2, while a-fetoprotein, hep-1 and glypican-3 were stained negative, which demonstrated that the HCS1220 cell line originating from the intestinal tissue." (PMID 30214379, 2018). "AFP, hep-1 and glypican-3, the well-used biomarkers for HCC, were negative and two well-known tumor markers for colon cancer, CK20, CDX2 were positive, clearly indicating that xenograft tumor were derived from intestinal tissue." (PMID 30214379, 2018).
esophageal cancer (4 papers, 2017 to 2025). A primary or metastatic malignant neoplasm involving the esophagus. "It is well known that GPC3 is not only expressed in HCC but also expressed in squamous non-small cell lung cancer, esophageal cancer and other cancer types." (PMID 28881778, 2017).
hepatoid adenocarcinoma (4 papers, 2020 to 2026). An adenocarcinoma with morphologic characteristics similar to hepatocellular carcinoma, arising from an anatomic site other than the liver. "In a previous study of hepatoid adenocarcinomas, AFP was positive in 80% cases, SALL4 was positive in 47%, HepPar‐1 was positive in 69%, and GPC3 was positive in 56%." (PMID 41190289, 2026).
intrahepatic cholangiocarcinoma (4 papers, 2017 to 2025). A carcinoma that arises from the intrahepatic bile duct epithelium in any site of the intrahepatic biliary tree. "The aim of this study was to investigate the prognostic value of arginase-1 (Arg-1) and glypican-3 (GPC-3) in patients with intrahepatic cholangiocarcinoma (ICC)." (PMID 34715880, 2021).
liposarcoma (4 papers, 2020 to 2025). A usually painless malignant tumor that arises from adipose tissue. "RNAseq data profiling GPC3 expression in HCC, SCC, liposarcoma, colorectal adenocarcinoma (CRC), and serous ovarian cancers (OC) was accessed from the Cancer Genome Atlas Program (TCGA) and showed varying degrees of GPC mRNA expression." (PMID 35507536, 2022). "However, HCC, SCC, and myxoid/round liposarcoma (MRCLS) samples in the TMAs showed appreciable levels of membrane and cytoplasmic GPC3 expression (H-score ≥ 30) with >20% prevalence." (PMID 35507536, 2022). "GPC3 protein expression was observed in >30% of samples from patients with HCC, squamous cell carcinoma of the lung (SCC), Merkel cell carcinoma (MCC), and liposarcoma demonstrating its attractiveness as a CAR tumor antigen target." (PMID 35507536, 2022).
malignant rhabdoid tumors (4 papers, 2013 to 2025). "On the contrary, glypican-3 has been found positive in a significant percentage of malignant rhabdoid tumors; thus, it seems to be a useful marker, along with Ca 125, for the distinction of ES from malignant rhabdoid tumors." (PMID 23691400, 2013).
Obesity (4 papers, 2019 to 2026). Accumulation of substantial excess body fat. "In addition, IR was also associated with increased levels of hepatic GPC3 expression, suggesting that obesity may predict better response to GPC3-CAR-T cell therapy." (PMID 37266440, 2023). "GPC3 is a potential target gene for microRNA Mir717, and the genes that Mir717 may target are related to mammalian obesity and other related phenotypes." (PMID 31316554, 2019).
pancreatic ductal adenocarcinoma (4 papers, 2020 to 2025). An infiltrating adenocarcinoma that arises from the epithelial cells of the pancreas. "Background/Objectives: One study of pancreatic ductal adenocarcinoma has found expression of glypican-3 (GPC3) and cytokeratin-19 (CK19) determined by immunohistochemistry to be associated with higher stage and grade disease, with a more adverse prognosis." (PMID 39598037, 2024).
renal cell carcinoma (4 papers, 2014 to 2023). "We suggest that the GPC3 gene reduces the rate of cell proliferation through cell cycle arrest during the G1 phase in renal cell carcinoma." (PMID 25168166, 2014). "In the present study, we investigated the mechanisms of action of GPC3 in renal cell carcinoma using colony formation, cell proliferation, cell cycle progression and apoptosis assays to assess the potential role of GPC3 in this type of cancer." (PMID 25168166, 2014). "To verify whether GPC3 overexpression arrests the cell cycle in renal cell carcinoma, we used flow cytometry to perform cell cycle analysis." (PMID 25168166, 2014). "Further, apoptosis was not induced in the renal cell carcinoma cell lines overexpressing GPC3, and there was an increase in the cell population during the G1 phase in the cell cycle." (PMID 25168166, 2014).
seminoma (4 papers, 2015 to 2024). A radiosensitive malignant germ cell tumor found in the testis (especially undescended), and extragonadal sites (anterior mediastinum and pineal gland). "Identification of the different subtypes was achieved by additional staining with OCT4 for EC, PLAP for seminoma and Glypican 3 for YST." (PMID 32363003, 2020). "Some research conducted a series of panels constituting OCT 3/4, CD117, GPC3, and CD30 with good sensitivity and specificity in differentiating seminomas, YSTs, and EC, respectively." (PMID 39001344, 2024). "In addition IGCNU, all examined seminomas and embryonic carcinomas did not express CK19, Glypican-3, or AFP." (PMID 25889715, 2015).
squamous cell carcinoma (4 papers, 2014 to 2026). A carcinoma arising from squamous epithelial cells. "In a recent study, Gailey and Bellizzi analyzed GPC3 protein expression in squamous cell carcinoma (SCCs) of diverse anatomic sites and in invasive urothelial carcinomas from the urinary bladder." (PMID 25168166, 2014). "In addition, a-l-fucosidase, r-glutamyl transferase, glypican-3, and squamous cell carcinoma antigen are used as a marker." (PMID 24999482, 2014). "Gailey and Bellizzi also observed an absence of GPC3 expression in squamous cell carcinomas (SCCs) from the penis, skin and vulva." (PMID 25168166, 2014).
thyroid cancer (4 papers, 2010 to 2022). "Several studies indicate that aberrant Hh signaling plays a role in thyroid neoplasia, and GPC3 expression has also been investigated in thyroid cancer." (PMID 27249794, 2016). "Recently, we established a quantitative ELISA assay for GPC3 and investigated its clinical usefulness for the diagnosis of thyroid cancer." (PMID 20652009, 2010). "When we performed immunohistochemical analysis of GPC3 in thyroid cancer, GPC3 was scarcely expressed in normal thyroid glands, but was dramatically enhanced in certain types of cancers including 100% of follicular carcinomas (20/20 cases) and 70% of papillary carcinomas (48/69 cases)." (PMID 20652009, 2010). "Further studies are required to characterize GPC3-mediated cell signaling in thyroid cancer." (PMID 20652009, 2010). "When the GPC3 gene was transfected into a human thyroid cancer cell line, TAD2, cell growth was dramatically suppressed in the wild type of GPC3 transfectants, but not markedly suppressed in the GPC3 oligosaccharide mutants." (PMID 20652009, 2010).
urothelial carcinoma (4 papers, 2014 to 2020). A malignant neoplasm derived from the transitional epithelium of the urinary tract (urinary bladder, ureter, urethra, or renal pelvis). "In urothelial carcinoma (UC), GPC3 has a higher positive rate in malignant UC (43.6% vs 13.3%), which is not expressed in normal urothelium." (PMID 32127929, 2020). "In conclusion, in our study GPC3 was expressed in a significant proportion of urothelial carcinomas, mostly in the high grade tumors." (PMID 25896897, 2015). "GPC3 expression defined in urothelial carcinomas suggested that GPC3-derived vaccines might have an immunotherapeutic effect on these tumors." (PMID 25896897, 2015). "The aim of this study was to investigate the immunohistochemical expression of GPC3 in the non-neoplastic urothelium and in urothelial carcinoma (UC)." (PMID 25896897, 2015). "GPC3 staining may be useful in differentiating between non-neoplastic and neoplastic urothelium as well as high grade and low grade urothelial carcinoma especially in small punch biopsies." (PMID 25896897, 2015).
breast tumors (3 papers, 2020 to 2025). "Wnt-signaling pathway: LM3 breast tumor cells, when overexpressing GPC3, can secrete GPC3 to competitively interact with Wnt ligands, thereby preventing their binding to the Wnt receptor and consequently curbing the canonical Wnt-signaling pathway." (PMID 40422229, 2025). "For example, human glypican 3 (GPC3) is upregulated in most hepatocarcinoma and indicative of differentiation grade, but is downregulated in some non-liver tumors including ovarian or breast tumors." (PMID 31826854, 2020). "Heparan sulfate proteoglycans (HSPGs) are abnormally expressed in BC tissues: GPC1 is overexpressed, while GPC3 and GCP5 show reduced expression, and GPC4 expression is downregulated in metastatic breast tumors compared with nonmetastatic breast tumors." (PMID 40443562, 2025).
chronic hepatitis C (3 papers, 2010 to 2026). "Nonetheless, a recent study reported GPC-3 immunoreactivity in inflammatory liver biopsies from patients with chronic hepatitis C and a further study reported the up-regulation of GPC-3 in monocyte-derived DC after maturation." (PMID 20465843, 2010).
embryonal carcinoma (3 papers, 2015 to 2022). A non-seminomatous malignant germ cell tumor characterized by the presence of large germ cells with abundant cytoplasm resembling epithelial cells, geographic necrosis, high mitotic activity, and pseudoglandular and pseudopapillary structures formation. "Contrary to the embryonal carcinoma cells, these cells forming gland-like spaces expressed GPC3 and AFP and showed stronger reactivity for pooled cytokeratins than the embryonal carcinoma component." (PMID 26880963, 2016).
hepatocellular adenoma (3 papers, 2014 to 2024). A benign epithelial neoplasm arising from the hepatocytes. "Recently, several studies have demonstrated that GPC3 is positive in most HCC, and positive immunostaining has been detected in 52.5% to 85% of HCC, but not in healthy livers or various benign liver lesions, including cirrhotic livers, hepatocellular adenoma and focal nodular hyperplasia." (PMID 24498024, 2014). "Positive staining for GPC-3 is observed in approximately 80–90% of HCC cases, but negative in the normal liver, hepatocellular adenoma (HCA), focal nodular hyperplasia (FNH), and large regenerative nodule." (PMID 34071338, 2021).
liver tumor (3 papers, 2012 to 2022). "In conclusion, our report further demonstrates the active role of miRNA deregulations in oncogenic processes and brings new information about the complex miRNA:GPC3 relationships occurring in liver tumors." (PMID 28476031, 2017). "We next investigated in more details expression of miR-4510 and GPC3 mRNA in liver tumor samples." (PMID 28476031, 2017). "Markers of liver tumours, such as Glypican-3, AFP and HepPar1, were present in HC-AFW1." (PMID 22666492, 2012).
pneumonia (3 papers, 2017 to 2023). An acute, acute and chronic, or chronic inflammation focally or diffusely affecting the lung parenchyma, caused by an infection in one or both of the lungs (by bacteria, viruses, fungi, or mycoplasma.). "Expression of GPC3 in peripheral circulation of severe pneumonia-associated ARDS patients progressively increased over time (admission day, day 3, day 7) compared with healthy persons or severe pneumonia patients alone." (PMID 28510121, 2017). "The investigators further showed that circulating levels of GPC3 were increased in ARDS induced by severe pneumonia as a model of infection-dominated disease, as well as in ARDS induced by acute pancreatitis as a model of non-infection-based disease." (PMID 28510121, 2017). "GPC3 was recently selected and proposed as a biomarker in patients with severe pneumonia and ARDS." (PMID 28510121, 2017). "We proposed that the circulating level of glypican-3 may correlate with the severity of pneumonia as potential biomarker to predict the occurrence of ARDS." (PMID 28510121, 2017). "Increased serum levels of GPC3 have been demonstrated in ARDS patients with severe pneumonia." (PMID 28510121, 2017).
preeclampsia (3 papers, 2010 to 2023). Preeclampsia is a hypertensive disorder of pregnancy that is characterized by new-onset hypertension with proteinuria presenting after 20 weeks of gestation, and depending on mild or severe forms may initially present with severe headache, visual disturbances, and hyperreflexia. "Low expression of GPC3 in placenta of preeclampsia results in an enhanced influx of TFPI2 into the maternal circulation." (PMID 37238908, 2023).
sarcoma (3 papers, 2019 to 2023). A usually aggressive malignant neoplasm of the soft tissue or bone. "In this review, we provide an update of the CAR T cell therapies that are currently being tested in pediatric sarcoma clinical trials, including those targeting tumors that express HER2, NY-ESO, GD2, EGFR, GPC3, B7-H3, and MAGE-A4." (PMID 34572932, 2021).
Simpson-Golabi-Behmel syndrome type 1 (3 papers, 2020 to 2024). Any Simpson-Golabi-Behmel syndrome in which the cause of the disease is a mutation in the GPC3 gene. "GPC3 deletion mutation can help in diagnosis of Simpson-Golabi-Behmel syndrome type 1 (SGBS1), which is a serious genetic disease." (PMID 33302876, 2020).
colorectal adenocarcinoma (2 papers, 2015 to 2022). The most common type of colorectal carcinoma. "Glypican-1 and Glypican-3 dysregulation is related to Notum and β-catenin alterations mostly in AOM/DSS-induced colorectal adenocarcinomas and in human colorectal tumors but also, in some cases, in early murine CRC stages." (PMID 26517809, 2015).
endometriosis (2 papers, 2023 to 2025). The growth of functional endometrial tissue in anatomic sites outside the uterine body. "The GPC3 protein is detectable in the follicle fluid of women, and it is increased or decreased in endometriosis patients or women with diminished ovarian reserves, respectively, implying roles of GPC3 in the reproductive function of females." (PMID 40422229, 2025).